CD47 (CD47 molecule)
Description:
Adhesive protein that mediates cell-to-cell interactions. Acts as a receptor for thrombospondin THBS1 and as modulator of integrin signaling through the activation of heterotrimeric G proteins. Involved in signal transduction, cardiovascular homeostasis, inflammation, apoptosis, angiogenesis, cellular self-renewal, and immunoregulation. Plays a role in modulating pulmonary endothelin EDN1 signaling. Modulates nitrous oxide (NO) signaling, in response to THBS1, hence playing a role as a pressor agent, supporting blood pressure (By similarity). Plays an important role in memory formation and synaptic plasticity in the hippocampus (By similarity). Receptor for SIRPA, binding to which prevents maturation of immature dendritic cells and inhibits cytokine production by mature dendritic cells. Interaction with SIRPG mediates cell-cell adhesion, enhances superantigen-dependent T-cell-mediated proliferation and costimulates T-cell activation. Positively modulates FAS-dependent apoptosis in T-cells, perhaps by enhancing FAS clustering (By similarity). Plays a role in suppressing angiogenesis and may be involved in metabolic dysregulation during normal aging. In response to THBS1, negatively modulates wound healing (By similarity). Inhibits stem cell self-renewal, in response to THBS1, probably by regulation of the stem cell transcription factors POU5F1/OCT4, SOX2, MYC/c-Myc and KLF4 (By similarity). May play a role in membrane transport and/or integrin dependent signal transduction. May prevent premature elimination of red blood cells (By similarity).
Synonyms: IAP; MER6; OA3
Tractability: Antibody: a drug acting on it is in phase 2 or 3 trials; UniProt places it where antibodies can reach, with high confidence; its Gene Ontology location is reachable by antibodies, with high confidence; UniProt predicts a signal peptide or a membrane-spanning region; the Human Protein Atlas places it where antibodies can reach. PROTAC: ubiquitination databases record sites on it; its protein half-life has been measured; a small molecule that binds it is known. Other modalities: a drug acting on it is in phase 2 or 3 trials.
Target class: Adhesion
Gene: Protein-coding gene on chromosome 3 (108,043,091 to 108,091,862, reverse strand). Ensembl gene ENSG00000196776.
Subcellular location: Cell membrane
Subcellular location (Human Protein Atlas): Plasma membrane; Vesicles
Pathways (Reactome):
Cell-Cell communication: Signal regulatory protein family interactions
Extracellular matrix organization: Integrin cell surface interactions
Hemostasis: Cell surface interactions at the vascular wall
Immune System: Neutrophil degranulation
Gene Ontology:
Molecular function: cell-cell adhesion mediator activity; fibrinogen binding; protein binding; thrombospondin receptor activity; protein binding involved in heterotypic cell-cell adhesion
Biological process: ATP export; cellular response to interleukin-12; positive regulation of cell population proliferation; positive regulation of cell-cell adhesion; positive regulation of T cell activation; regulation of interleukin-10 production; regulation of interleukin-12 production; regulation of interleukin-6 production; regulation of tumor necrosis factor production; regulation of type II interferon production; cell migration; cellular response to interleukin-1; cellular response to type II interferon; integrin-mediated signaling pathway; negative regulation of phagocytosis; positive regulation of inflammatory response; positive regulation of monocyte extravasation; positive regulation of phagocytosis; positive regulation of stress fiber assembly; regulation of Fc receptor mediated stimulatory signaling pathway; regulation of nitric oxide biosynthetic process; cell-cell adhesion; heterotypic cell-cell adhesion; positive regulation of immune system process
Cellular component: cell surface; plasma membrane; extracellular exosome; specific granule membrane; tertiary granule membrane
Genetic constraint (gnomAD): Loss-of-function variants: 2 observed, 8.68 expected, observed/expected ratio (o/e) 0.23, 90% interval 0.093 to 0.73. That is too few expected variants to judge how well the gene tolerates losing a copy. Missense variants: 105 observed, 135.08 expected, observed/expected ratio (o/e) 0.78, 90% interval 0.66 to 0.91. Synonymous variants: 64 observed, 53.42 expected, observed/expected ratio (o/e) 1.2, 90% interval 0.98 to 1.48.
Homologues: Orthologues: chimpanzee CD47 (99% identical), macaque CD47 (92% identical), guinea pig CD47 (73% identical), pig CD47 (72% identical), mouse Cd47 (72% identical), rat Cd47 (69% identical), dog CD47 (60% identical), rat LOC100909977 (42% identical).
Diseases named in the same sentence as CD47 in open-access papers:
CD47 is named in the same sentence as 390 diseases in open-access papers, as found by Europe PMC text mining. Sharing a sentence is not in itself a finding about the gene and the disease. The quoted sentences say what the papers report.
breast carcinoma (200 papers, 2013 to 2026). "CD47 expression has also been shown to be overexpressed in several breast cancer cell lines and is associated with overall increased cancer cell survival." (PMID 40051976, 2024). "Some reports have documented that high expression of CD47 is associated with aggressive breast cancer features and poor prognosis." (PMID 36598153, 2023). "Our current analysis of TCGA data and PANCAN_RPPA data and from breast cancer patients show that elevated expression of Kaiso is associated with increased CD47 and SIRPA and decreased THPS1 in ER-negative basal-like tumors." (PMID 37190208, 2023). "Ratios of 50:1 are used to kill 30% of SKBR3 breast cancer cells opsonized with Trastuzumab, and killing increases only two-fold on a CD47-deficient target." (PMID 35795660, 2022). "In breast carcinoma and small-cell lung cancer, CD47 expression has been reported to be associated with advanced stage at diagnosis, lymphogenous metastasis, and recurrence." (PMID 36611344, 2022). "Zhang and colleagues report that the deficiency in CD47 leads to cancer stem cell depletion and datasets derived from thousands of breast cancer patients revealed that CD47 expression correlates with HIF target gene expression and with patient mortality." (PMID 36233088, 2022). "Although CD47 expression is shown to be associated with the development of numerous tumors, its role in breast cancer is less-well characterized." (PMID 35860564, 2022). "A study reported that TNF-NFKB1 signaling can directly regulate CD47 by interacting with a constituent enhancer located within a CD47-associated super-enhancer specific to breast cancer." (PMID 34349643, 2021). "Co-expression of GRP78 and CD47 is associated with a significant decrease in survival in HR+/HER2- breast cancer." (PMID 34135901, 2021). "Here, we demonstrated that ICRP induced P-eIF2α and increased the “eat me signals” CRT, HSP70 and HSP90 on breast cancer cell surface, and also decreased the surface-associated “don ́t eat me” signal CD47." (PMID 33531687, 2021). "CD47 expression was reported to correlate with HIF1 target gene expression in breast cancer patients and ultimately associate with poor patient survival." (PMID 29707136, 2018). "In breast cancer patients who received endocrine targeting therapy, co-expression of CD47 and GRP78 was associated with reduced RFS." (PMID 28815041, 2017). "Reducing either HIF-1 or CD47 expression can cause an increase in bone-marrow derived macrophage phagocytosis of breast cancer cells." (PMID 27706047, 2016). "In breast cancer, CD47 is associated with epithelial-mesenchymal transition and poor DFS." (PMID 37685859, 2023). "Notably, the super-enhancer linked to CD47 has been annotated before in breast cancer and we show evidence of the increased activity of the constituent enhancers specifically within the cancer-epithelial cell types." (PMID 37685859, 2023). "Interestingly, we found a second cluster of cancer-cell-specific enhancers that are linked with the expression of CD47 and overlap with a previously annotated super-enhancer in breast cancer." (PMID 37685859, 2023). "CD47 overexpression has been reported in various types of malignancy and is associated with a poor prognosis in solid and hematologic malignancies, including non-small cell lung cancer, breast cancer, stomach cancer, and non-Hodgkin lymphoma." (PMID 33917794, 2021). "Furthermore, considering that miR‐708 was demonstrated to be associated with breast cancer clinical characteristics and good prognosis, we then analysed clinical relevance of CD47 in breast cancer." (PMID 31273952, 2019). "However, Kaplan–Meier analysis and log-rank test showed that high CD47 expression in breast cancer tissues had a limited association with reduced 5-year disease-free survival (5-DFS) (P = 0.057)." (PMID 31528120, 2019).
breast carcinoma (continued). "Furthermore, our clinical data suggest miR‐708 and CD47 expression in primary breast cancer tissues is associated with patients’ prognosis and response to chemotherapy." (PMID 31273952, 2019). "Finally we report that the TNF-NFKB1 signalling pathway directly regulates CD47 by interacting with a constituent enhancer located within a CD47-associated SE specific to breast cancer." (PMID 28378740, 2017). "Moreover, GRP78 and CD47 co-expression is associated with poor prognosis in breast cancer patients, suggesting the existence of crosstalk between UPR and immunity that regulates therapeutic responses in breast cancer." (PMID 28815041, 2017). "Recent studies in hepatocellular carcinoma stem cells and a breast carcinoma cell line demonstrated that reducing CD47 expression results in loss of stem cell character, suggesting that CD47 signaling differentially regulates normal versus malignant stem cells." (PMID 26840086, 2016). "Detection and targeting of MET and CD47 may thus provide a rational basis for risk stratification and treatment of patients with luminal-type breast cancer." (PMID 25230070, 2014). "Similarly, analyses of SEs in four patient derived-xenografted (PDX) breast tumour samples revealed that an ER+ PR+ breast cancer sample has the breast cancer SE associated with CD47 while the other three PDX breast tumour samples (triple negative: ER−, PR−, Her2−) do not." (PMID 28378740, 2017). "Here, we identified a bifunctional super-enhancer that regulates the expression of cancer-promoting genes LINC00636 and CD47 in breast cancer." (PMID 42183347, 2026). "Analysis of the Cancer Cell Line Encyclopedia (CCLE) revealed a positive correlation between DNAJC13 and CD47 expression across multiple cancer cell lines, including breast cancer, melanoma, and colon cancer." (PMID 41601654, 2026). "Preclinical studies demonstrate that IgG1 antibodies combined with CD47 inhibitors improve the tumor-killing efficacy of TANs against breast cancer cells." (PMID 40568594, 2025). "Cell membrane-coated magnetic nanoparticles (gCM-MNs) stimulate macrophage repolarization (M2→M1) and block CD47–SIRPα signaling, reducing metastatic spread in melanoma and breast cancer." (PMID 41409250, 2025). "For example, studies have documented high CD47 expression in esophageal cancer, gastric cancer, colorectal cancer, hepatocellular carcinoma, lung cancer, breast cancer, endometrial cancer, kidney cancer, and nasopharyngeal cancer." (PMID 40765033, 2025). "Breast cancer, known for its relatively low response rates to T cell ICIs and high CD47 expression 9-11, has been challenging to treat with immunotherapy." (PMID 39744689, 2025). "Patients with high CD47 expression have been shown to demonstrate poorer outcomes compared to those with low CD47 expression in several indications, including breast cancer, HNSCC and acute myeloid leukemia." (PMID 41415295, 2025). "In breast cancer, CD47 expression is upregulated by hypoxia-inducible factor 1 (HIF-1), particularly under hypoxic conditions." (PMID 40396172, 2025). "CD47 antibodies induced a caspase-independent cell death pathway in breast cancer and leukemia cells." (PMID 38495618, 2024). "On the contrary, radiation-resistant breast cancer cells and irradiated breast tumors are found to rely on high CD47 expression for their survival." (PMID 39039207, 2024). "In the realm of breast cancer treatments, a preclinical study suggests that overcoming resistance to trastuzumab in HER2/Neu+ breast cancer can be achieved by combining CD47 blockade with trastuzumab." (PMID 39040441, 2024). "D3L-001, a bispecific antibody against HER2 and CD47 was investigated in HER-2+ breast cancer cell lines HCC1954, JIMT-1, and patient-sourced xenograft models of breast cancer." (PMID 39660126, 2024).
breast carcinoma (continued). "For example, a key myeloid checkpoint involved in the abscopal effect, CD47, has been shown to be overexpressed in radioresistant tumors from multiple types of primary tumor, including breast cancer and a model of glioblastoma." (PMID 39695143, 2024). "Contrary to its role in untransformed healthy cells, CD47 supports self-renewal of cancer stem cells (CSCs) in breast cancer and hepatocellular carcinoma." (PMID 39039207, 2024). "These trials reflect the growing interest and exploration of CD47-SIRPα targeted immunotherapy in the context of breast cancer." (PMID 39040441, 2024). "It was discovered that combining trastuzumab with anti-CD47 potentiated antibody-dependent cellular phagocytosis of human HER2+ breast cancer cells." (PMID 38892394, 2024). "Preclinical studies have demonstrated that anti-CD47 mAb decreases breast cancer cell proliferation and induces the death of breast cancer cells in vitro." (PMID 39040441, 2024). "The net outcome culminates in impaired T-cell lymphoma, breast cancer and melanoma growth in vivo especially when combined with anti-CD47, anti-CTLA-4 or anti-PD-1 depending on the animal model." (PMID 38831284, 2024). "High expression of CD47 can be observed on ovarian cancer, breast cancer, squamous cell carcinoma of the head and neck, gliomas, osteosarcoma, melanoma, glioblastoma, bladder cancer, colon cancer, hepatocellular cancer, and in myeloid leukemia stem cells." (PMID 38892394, 2024). "We inoculated control and Vtn knockdown breast cancer cells into mouse fat pads, treated the mice with IgG control or an anti-CD47 antibody every other day from day 7 to day 25, and measured tumor sizes." (PMID 38773982, 2024). "It has been observed that usage of anti-CD47 antibodies on mice with breast cancer substantially prolonged survival of the animals." (PMID 38892394, 2024). "HIF-1 increases CD47 expression by directly activating transcription of its gene in hypoxic breast cancer cells which consequently leads to inhibition of phagocytosis." (PMID 38892394, 2024). "Analysis of a human breast cancer database revealed that high CD47 expression is also correlated with increased HIF target gene expression and decreased patient survival." (PMID 38183060, 2024). "High expression of CD47 in breast cancer enables tumor cells to escape the attack of the innate immune system, which is closely related to the low immunogenicity of tumors." (PMID 39697556, 2024). "Macrophage checkpoint blockade, using the anti-CD47 antibody Magrolimab has been investigated in HER2+ breast cancer cells in combination with the anti-HER2 antibody Trastuzumab." (PMID 39660126, 2024). "CD47 is expressed in many tumors, such as breast cancer and anaplastic thyroid cancer, among others." (PMID 38404571, 2024). "To date, CD47 has been shown to induce senescence in endothelial cells, colorectal cancer cells, and breast cancer cells." (PMID 39039207, 2024). "CD47 blockade has been used to augment radiotherapy response in preclinical models of breast cancer and SCLC." (PMID 39695143, 2024). "Targeting CD47 has been widely studied in many types of cancer, including hematologic malignancies, lung cancer, colorectal cancer, and breast cancer." (PMID 39335665, 2024). "Then, in vivo experiments in mouse models were conducted to explore the probability of Vtn knockdown combined with anti-CD47 therapy in breast cancer." (PMID 38773982, 2024). "Here, we aimed to elucidate intratumoral CD8+ T cell responses generated upon dual CD47 and PD‐L1 blockade in an orthotopic model of breast cancer." (PMID 39584189, 2024). "In another study, it was found that the prognosis of breast cancer patients with high levels of CD47 expression was significantly worse compared to that of patients with low CD47 expression." (PMID 39795582, 2024).